LMNA (lamin A/C)
Diseases named in the same sentence as LMNA in open-access papers (continued):
Sharing a sentence is not in itself a finding about the gene and the disease.
lipodystrophy (continued). "Mutations in the human LMNA gene cause dysregulation of adipose tissue referred to as lipodystrophy (Wiltshire, Hegele, Innes & Brownell, 2013)." (PMID 29575479, 2018). "In accordance, several studies have confirmed that LMNA mutations specific for lipodystrophies result in modified interactions of the protein C-terminal domain with distinctive partners in vitro." (PMID 29578370, 2018). "The common duplication of PMP22 was ruled out by clinical-grade testing, and genes known to cause lipodystrophy (LMNA, PPARG, EMD, AGPAT2, BSCL2) were also sequenced." (PMID 28050599, 2017). "Mutations in the LMNA gene are associated with over 15 disease phenotypes, including striated muscle diseases, peripheral neuropathy, lipodystrophy, bone diseases, and premature ageing syndromes with multisystemic pathology." (PMID 27534416, 2017). "Mutations in the LMNA gene cause a number of clinical phenotypes, including muscular, peripheral neurogenic, lipodystrophies and premature ageing syndromes." (PMID 27585670, 2017). "We describe here a patient with a severe phenotype, congenital muscular dystrophy (L-CMD) and lipodystrophy, in whom we detected a novel heterozygous LMNA p.R388P de novo mutation." (PMID 28125586, 2017). "Mutations in several genes have been found in patients with inherited lipodystrophies, including mutations in LMNA, PPARG, AKT2 and ZMPSTE24 in partial lipodystrophy, and mutations in AGPAT2, BSCL2, CAV1 and PTRF in congenital total lipodystrophy." (PMID 26987365, 2016). "Several diseases are associated with mutations in LMNA, including progeria, lipodystrophy, muscular dystrophy and peripheral neuropathy." (PMID 20526372, 2010). "Similarly, LMNA (lamin A/C), encoding a protein essential for nuclear structure, is frequently mutated in lipodystrophy, leading to adipocyte degeneration." (PMID 39944202, 2025). "Then, we evaluated whether FGF21 alone or FGF21/sTGFBR2 combination therapy improved metabolic dysfunction associated with lipodystrophy in an adipocyte-specific lamin A/C–knockout (LmnaADKO) mouse model." (PMID 40663389, 2025). "However, the pattern of affected muscles and the symptoms of lipodystrophy in some of the patients we examined suggested the LMNA gene as the cause of the disease." (PMID 39940784, 2025). "Interestingly, mutations in genes that encode nuclear lamina factors, such as LMNA, are linked to human aging and progeria syndromes and their malfunction results in a multitude of diseases, including muscle dystrophies and lipodystrophies." (PMID 36718841, 2023). "Besides causing lipodystrophy, mutations in the lamin A/C (LMNA) gene can lead to a wide spectrum of tissue-specific disorders including cardiac involvement." (PMID 35384599, 2022). "Heterozygous mutations of the LMNA gene encoding lamin A/C, the main nuclear intermediate filament proteins of the nuclear envelope, are responsible for complex diseases that can combine lipodystrophy, metabolic complications, osteoporosis and osteolysis, and signs of accelerated ageing." (PMID 35955791, 2022). "In summary, patients with atypical Werner syndrome caused by R133L heterozygous LMNA mutations may present with different types of lipodystrophies, which may present with partial or total body fat loss." (PMID 35281936, 2022). "Additionally, different from the mouse model, LMNA-KO rabbits showed biochemical features of lipodystrophy including loss of subcutaneous fat." (PMID 30705772, 2019). "Taken as a whole these studies show that lipodystrophy-causing LMNA mutations could result in several defects leading to defective adipocyte differentiation." (PMID 29578370, 2018). "LMNA mutations are responsible for the most frequent genetic form of lipodystrophy." (PMID 29578370, 2018).
lipodystrophy (continued). "The pathophysiological link between partial lipodystrophy and cellular senescence has been previously evoked not only for LMNA mutations but also with the description of lipodystrophy syndrome resulting from mutations in WRN which encodes the DNA helicase WRN, involved in DNA replication and repair." (PMID 27120622, 2016). "Mutations in PPARγ (PPARG) or lamin A/C (LMNA) can cause partial lipodystrophy." (PMID 27225296, 2016). "Several missense mutations in the LMNA gene have also been associated with atypical progeria syndromes, metabolic laminopathies and lipodystrophies, but it has been unclear whether their associated phenotypes are due to prelamin A accumulation." (PMID 26900797, 2016). "Hence, our results suggested that defects of the LMNA gene caused lipodystrophy in LMNA-KO rabbits." (PMID 30705772, 2019). "Additionally, we recently showed that several LMNA mutations, either leading to a lipodystrophy typical of the FPLD2 type, or associated with signs of premature ageing, also triggered vascular smooth muscle cell senescence with osteoblastic transdifferentiation and calcification." (PMID 29578370, 2018). "LMNA mutations can cause diverse phenotypes, including DCM, Emery-Dreifuss muscular dystrophy, limb-girdle muscular dystrophy, lipodystrophy, progeria syndrome, and restrictive dermopathy." (PMID 39070560, 2024). "In humans, LMNA variants can cause DCM with sudden death as well as diseases of striated muscles, lipodystrophy, neuropathies, and accelerated aging disorders." (PMID 37925523, 2023). "Given that individuals with LMNA mutations encoding lamins A/C R482 and R527P exhibit FPLD2 or symptoms such as lipodystrophy, we wanted to examine the properties of these mutant lamins in Drosophila adipose tissue." (PMID 37190051, 2023). "In our experience, PCOS secondary to a missense mutation in the LMNA gene, known as familial partial lipodystrophy type 2 (FPLD2), is the most frequent form of PCOS secondary to severe IR due to genetically determined lipodystrophy." (PMID 30131000, 2018). "Recently, we identified the p.R388P LMNA mutation as responsible for congenital muscular dystrophy (L-CMD) and lipodystrophy." (PMID 28441765, 2017). "Metreleptin use is associated with the lowering of triglycerides and haemoglobin A1c (HbA1c) in all lipodystrophy (n = 111), partial (n = 71) and generalised lipodystrophy (n = 41), and in LMNA, PPARG, AGPAT2 or BSCL2 subgroups (n = 72,13,21 and 21 respectively)." (PMID 37794082, 2023). "The mechanisms by which LMNA mutations cause muscular dystrophy and lipodystrophy are not well understood." (PMID 37190051, 2023). "BMI was lower after treatment in aggregated lipodystrophy, in generalized and partial subgroups, and in those with LMNA or BSCL2 mutations, but not PPARG or AGPAT2 mutations (Level 3 evidence)." (PMID 37794082, 2023). "These LMNA knockout (KO) rabbits displayed typical features of premature aging syndromes, including cardiac and skeletal muscle degeneration with fibrosis, impaired mobility, lipodystrophy, and bone abnormalities." (PMID 30705772, 2019). "For example, patients with FPLD that simultaneously carries LMNA p.S583L and p.T528M mutations showed a much more severe lipoatrophy than those harboring LMNA p.S583L only, while carriers of p.T528M variant do show not lipodystrophy at all." (PMID 39669119, 2024). "Although other lipodystrophy-causing mutations in LMNA do not directly modify the proteolytic maturation site of the protein, they could secondarily alter its maturation and result in prelamin A accumulation." (PMID 29578370, 2018).
lipodystrophy (continued). "In contrast to LMNA mutations involved in muscular dystrophies or cardiomyopathies, lipodystrophy-causing mutations do not disrupt the tridimensional structure of A-type lamins but modify a positively charged amino acid at the surface of their C-terminal domain." (PMID 29578370, 2018). "Notably, while many previously known lipodystrophy genes fell within the “lipocluster”, several did not (e.g., CAV1, PTRF, AKT2, CIDEC, LMNA)." (PMID 30940487, 2019).
muscular dystrophy (82 papers, 2007 to 2026). Muscular dystrophy (MD) refers to a group of more than 30 genetic diseases characterized by progressive weakness and degeneration of the skeletal muscles that control movement. "More specifically, we studied 3 different heterozygous mutations in the LMNA gene (which codes for A‐type lamins) that are known to be responsible for severe congenital muscular dystrophies." (PMID 39873289, 2025). "Lamin A/C-deficient mice (Lmna–/–, henceforth referred to as Lmna KO) develop severe muscular dystrophy and dilated cardiomyopathy and die around 6 to 10 weeks of age." (PMID 38778055, 2024). "This event corroborated previous reports that cardiac involvement in patients with LMNA mutations is more frequent and severe than in patients with other types of muscular dystrophies." (PMID 37974208, 2023). "Muscular dystrophies caused by deleterious variants in the LMNA gene are very rare (<1 per 1,000,000; ORPHA:157973)." (PMID 37035729, 2023). "Studies in cultured cells and model organisms of muscular dystrophy-associated LMNA mutations have revealed insights into potential pathomechanisms." (PMID 36120560, 2022). "The mechanisms by which mutations in the LMNA gene cause muscular dystrophy remain incompletely understood and are a topic of intense investigation." (PMID 36120560, 2022). "Muscular dystrophy, metabolic, neuropathic, and premature aging disorders are within the spectrum of disorders caused by mutations in LMNA (OMIM *150330)." (PMID 36555163, 2022). "A family originating from the south west of France and mutated in LMNA gene showed axonal sensorimotor neuropathy in association with muscular dystrophy, cardiac disease, and leuconychia." (PMID 33923914, 2021). "This tight regulation of phospho(T25)-cofilin-1 protein levels by ERK1/2 signaling is important for the maintenance of sarcomere structure and force generation, which participate in the development of muscular dystrophy caused by LMNA mutations." (PMID 34433058, 2021). "Severe cytoarchitectural abnormalities of skeletal muscles, particularly in soleus muscle, associated with increased connective tissue have been previously observed in Lmnap.H222P/H222P mice, a mouse model of muscular dystrophy caused by LMNA mutations." (PMID 34433058, 2021). "Despite the recent advances in deciphering the clinical description of muscular dystrophy caused by LMNA mutations, the molecular mechanisms leading to skeletal muscle damage remain to be determined." (PMID 34433058, 2021). "Muscular dystrophies due to heterozygous pathogenic variants in LMNA gene cover a broad spectrum of clinical presentations and severity with an age of onset ranging from the neonatal period to adulthood." (PMID 34240052, 2021). "Mutations in the LMNA gene, encoding the nuclear envelope A-type lamins, are responsible for muscular dystrophies, the most severe form being the LMNA-related congenital muscular dystrophy (L-CMD), with severe defects in myonucleus integrity." (PMID 32231000, 2020). "Preliminary data suggest an additional example of a rare variant, this time affecting the lamin/AC (LMNA) gene—related to muscular dystrophy—that was found in Canadian sprint hurdler Priscilla Lopes-Schliep." (PMID 31779250, 2019). "To investigate this, we examined artificial muscles generated from hiPSC derived from patients with muscular dystrophies caused by mutations in the LMNA gene." (PMID 29669293, 2018). "For instance, mutations in LMNA have been attributed to a class of disorders, collectively referred to as laminopathies; these range from muscular dystrophies to premature ageing disease to cardiomyopathies." (PMID 28994747, 2017). "These include Hutchinson Gilford progeria syndrome (HGPS, premature aging syndrome) caused by a truncated splicing mutation of the LMNA gene, resulting in the generation of progerin, muscular dystrophy, and familial dilated cardiomyopathy (DCM)." (PMID 27649756, 2016).
muscular dystrophy (continued). "A family originating from the southwest of France and with mutated LMNA gene showed axonal sensorimotor neuropathy in association with muscular dystrophy, cardiac disease and leukonychia." (PMID 27529282, 2016). "Mutations in the human LMNA gene cause muscular dystrophy that is often accompanied by heart disease." (PMID 25996830, 2015). "To better understand the pathogenesis caused by mutant lamins, we performed a structural and functional analysis on LMNA missense mutations identified in muscular dystrophy patients." (PMID 25996830, 2015). "Mutations in the human LMNA gene cause muscular dystrophy by mechanisms that are incompletely understood." (PMID 25996830, 2015). "In summary, early-onset LMNA-related muscular dystrophy is mostly caused by de novo mutations in the LMNA gene." (PMID 26098624, 2015). "Mutations in the human lamin A gene (LMNA) cause muscular dystrophies, type 2 Charcot-Marie Tooth disease, and premature aging diseases, among others." (PMID 17565385, 2007). "Thus far, the reported LMNA pathogenic and likely pathogenic variants of muscular dystrophy can occur at any domain of the lamin A/C." (PMID 36555163, 2022). "In the muscular dystrophies due to laminopathies the risk of arrhythmias increases with age (the penetrance of LMNA mutations is almost complete for cardiac phenotype), but their occurrence may be different in patients with emerinopathy and laminopathy." (PMID 33673224, 2021). "However, a few muscular dystrophy cases caused by recessive LMNA mutations have been described and defined as EDMD3." (PMID 33923914, 2021). "We further demonstrated that muscular dystrophy is associated with muscle cofilin-1 activation, which generated sarcomere disruption and alteration of force production, suggesting that cofilin-1 overexpression is a pathological event in muscular dystrophy caused by LMNA mutations." (PMID 34433058, 2021). "To date, there are multiple hypotheses regarding the onset of muscular dystrophies due to genetic mutations on LMNA or genes encoding for lamin A/C-associated proteins." (PMID 30781376, 2019). "Moreover, Samp1 is absent from the nuclear poles in EDMD2 myotubes, which shows that LMNA mutations associated with muscular dystrophy, due to reduced prelamin A levels in muscle cell nuclei, impair Samp1 anchorage." (PMID 30326651, 2018). "While muscle biopsies are now rarely performed in suspected cases of LMNA mutations causing muscular dystrophy, previous reports have shown that some LMNA muscular dystrophy patients have marked inflammatory cell infiltrates, although without noted upregulation of MHC." (PMID 29610677, 2018). "Thus, our results suggest that blocking the signaling pathway and maintaining the oxidative state of the diseased muscle are potential therapies for muscular dystrophy patients with LMNA mutations." (PMID 25996830, 2015). "In addition, mutations in both EMD and LMNA are involved in the Emery–Dreifuss muscular dystrophy." (PMID 33722199, 2021). "Thus, muscular dystrophies associated with mutations in the A-type lamin gene, LMNA, may be associated with decreased satellite cell differentiation, causing depressed regeneration in addition to reduced myofiber stability." (PMID 21603621, 2011). "Among other muscular dystrophies, 20 of 24 patients (83.3%) had variants in LAMA2 (n = 6), LMNA (n = 5), COL6A1 (n = 4), CHKB (n = 2), COL6A2 (n = 2), and COL6A3 (n = 1)." (PMID 40494860, 2025). "LMNA-KO rabbits demonstrated that severe growth retardation as well as muscular dystrophy." (PMID 30705772, 2019).
muscular dystrophy (continued). "Among muscular dystrophies, EDMD1 is linked to emerin mutations (EMD gene), EDMD2 and limb -girdle muscular dystrophy type 1B are caused by dominant lamin A/C mutations (LMNA gene), other forms of EDMD are caused by nesprin (SYNE1 and SYNE2 genes), FHL1, SUN1, or SUN2 mutations." (PMID 30781376, 2019). "Cardiomyopathies occurring in the absence of muscular dystrophy have been so far mostly linked to LMNA mutations, although cases related to nesprin gene defects have also been reported, and an association of LMNA with modifier gene variants has been suggested." (PMID 30781376, 2019). "It is worth noting that mice lacking A-type lamins develop a muscular dystrophy phenotype, consistent with a wide range of human LMNA mutations associated with this disease." (PMID 30282816, 2018). "LMNA H222P mutated gene knockin mice exhibited conduction defects, chamber dilation, increased fibrosis and lack of hypertrophy, and also showed muscular dystrophy and death at 4–9 months of age." (PMID 21151901, 2010). "An automated process has been developed for the detection of deletions, duplications/insertions and point mutations in any gene or family of genes and has been applied to ten genes known to bear mutations that cause muscular dystrophy: DMD; CAV3; CAPN3; FKRP; TRIM32; LMNA; SGCA; SGCB; SGCG; SGCD." (PMID 19835634, 2009). "Further, there are muscular dystrophies with similar symptoms to FSHD, that are linked with genes of the nuclear envelope: striated muscle laminopathies (e.g. Emery–Dreifuss-muscular-dystrophy and limb-girdle-muscular-dystrophy 1B) are caused by mutations in EMD, LMNA or SYNE1, among others." (PMID 38796645, 2024). "Similar to a previous observation that isolated cardiac involvement was predominantly found in patients with LMNA mutations located in the a-helical rod domain, none of the affected family members presented with muscular dystrophy or other organ system involvement." (PMID 24349489, 2013). "In addition, a cohort of 84 patients diagnosed with LMNA-related muscular dystrophy were also analyzed (EDMD, 38%; L-CMD, 49%; LGMD1B, 13%)." (PMID 37035729, 2023). "While at birth, wild-type, heterozygous and homozygous LMNA Δ8–11 mice are indistinguishable, after 2–3 weeks from birth, LMNA Δ8–11 −/− mice show a reduction in growth and display typical traits of muscular dystrophy, dying before 8 weeks of age." (PMID 33917623, 2021). "Whole exome sequencing (WES) revealed a heterozygous c.29C > T; p.T10I missense pathogenic variant in LMNA, which encodes lamins A and C. Muscle biopsy confirmed JDM rather than muscular dystrophy, showing perifascicular atrophy and perivascular mononuclear cell infiltration." (PMID 29610677, 2018). "However, for most LMNA-related muscular dystrophies, the mutant lamin A/C proteins with one single amino acid change did not result in direct loss of function, although some mutant lamins were suggested to be associated with disrupted nuclear structure or altered protein dynamics." (PMID 36555163, 2022).